B4GALT1-AS1 (B4GALT1 antisense RNA 1)
Gene: Long non-coding RNA gene on chromosome 9 (33,166,789 to 33,182,865, forward strand). Ensembl gene ENSG00000233554.
Gene Ontology:
Biological process: SRP-dependent cotranslational protein targeting to membrane, signal sequence recognition
Cellular component: signal recognition particle, endoplasmic reticulum targeting